SNORA12 (small nucleolar RNA, H/ACA box 12)
Synonyms: U108
Gene: Small nucleolar RNA gene on chromosome 10 (100,237,156 to 100,237,302, reverse strand). Ensembl gene ENSG00000212464.
Gene Ontology:
Biological process: RNA processing
Cellular component: nucleolus
Homologues: Orthologues: macaque SNORA12 (99% identical), chimpanzee SNORA12 (99% identical), pig SNORA12 (87% identical), rabbit SNORA12 (84% identical), guinea pig SNORA12 (79% identical), mouse Gm24336 (77% identical), rat Snora12 (77% identical).
Diseases named in the same sentence as SNORA12 in open-access papers:
SNORA12 is named in the same sentence as 16 diseases in open-access papers, as found by Europe PMC text mining. Sharing a sentence is not in itself a finding about the gene and the disease. The quoted sentences say what the papers report.
systemic lupus erythematosus (2 papers, 2023 to 2025). An autoimmune multi-organ disease typically associated with vasculopathy and autoantibody production. "SNORA12 expression is downregulated in T cells from systemic lupus erythematosus (SLE) patients and regulates the expression of CD69, HIST1H4K by promoting interferon production of T cells." (PMID 37006268, 2023).
virus infection (2 papers, 2014 to 2022). "While the function of SNORA12 in HRV infection remains to be determined, changes in SNORA12 gene expression during virus infection have been observed." (PMID 35344303, 2022). "Considering these findings were highly relevant to virus infection, we subsequently focused on investigating the effect of DNA methylation on SNORA12 gene expression." (PMID 24947756, 2014). "Given virus infection and other inflammatory diseases have been shown to affect the expression of snoRNA’s and other non coding RNAs, these findings suggest that SNORA12 is a component of the antiviral or inflammatory processes within the airway epithelium." (PMID 24947756, 2014). "While the function of SNORA12 in HRV infection remains to be determined, we observed changes in SNORA12 gene expression during virus infection." (PMID 24947756, 2014).
alcohol steatohepatitis (1 paper, 2024). "According to these studies, we selected four snoRNAs (snoRA12, snoRA47, snoRA80E, and snoRD126) for exploration in the context of non-viral-related causes, including non-alcoholic steatohepatitis (NASH), non-alcoholic fatty liver diseases (NAFLD), and alcohol steatohepatitis." (PMID 39022679, 2024).
breast carcinoma (1 paper, 2026). "High SNORA12 expression was associated with poor prognosis in glioma (HR = 1.31, p = 0.006) but favorable outcomes in pancreatic (HR = 0.51, p = 0.01) and breast cancer (HR = 0.56, p = 0.02)." (PMID 41898368, 2026).
cervical cancer (1 paper, 2021). A primary or metastatic malignant neoplasm involving the cervix. "In particular, tumor-related platelet activation by downregulation of RGS18 and an immune suppression by upregulation of both SNORA12 and SNORD97 may be essential mechanisms for cervical cancer development and progression." (PMID 34827689, 2021).
cervical squamous cell carcinoma (1 paper, 2021). A squamous cell carcinoma arising from the cervical epithelium. "The downregulation of SNORA12 and SNORD97 in tissues from patients with cervical squamous cell carcinoma implies that their secretion from cancer cells may help to evade host immunity against tumors through suppression of both systemic lymphopenia and lymphocyte activity in the TME." (PMID 34827689, 2021).
lung adenocarcinoma (1 paper, 2024). A carcinoma that arises from the lung and is characterized by the presence of malignant glandular epithelial cells. "The prognosis of patients with lung adenocarcinoma was significantly affected by six genes (KRT6A, VEGFC, KRT14, KRT17, SNORA12, and KRT81) related to FSTL3." (PMID 38240936, 2024). "Concurrently, we will delve into the interactions between FSTL3 and other pertinent genes, such as KRT6A, VEGFC, KRT14, KRT17, SNORA12, and KRT81, to enhance our understanding of its role in lung adenocarcinoma progression and to pinpoint novel therapeutic targets." (PMID 38240936, 2024).
lung carcinoma (1 paper, 2020). "While SNORA12 is found upregulated in lung cancer, NME1-NME2 upregulation is described to promote the survival of AML cells." (PMID 32817744, 2020).
osteosarcoma (1 paper, 2026). A usually aggressive malignant bone-forming mesenchymal neoplasm, predominantly affecting adolescents and young adults. "This study investigates the expression pattern, prognostic significance, and immune correlation of SNORA12 across cancers, with mechanistic validation in osteosarcoma." (PMID 41898368, 2026). "Experimentally, overexpression of SNORA12 in osteosarcoma cells and primary NK cells significantly upregulated TIGIT at both the mRNA and protein levels, while SNORA12 knockdown in NK92 cells reduced TIGIT expression." (PMID 41898368, 2026). "In vitro, the regulatory effect of SNORA12 on the immune checkpoint TIGIT was validated by overexpression and knockdown experiments in osteosarcoma cell lines (SW1353, U2OS) and NK cells." (PMID 41898368, 2026).
tumor (3 papers, 2021 to 2026). "In tumor tissues, snoRA12, snoRA47 and snoRA80E were upregulated, while snoRD-126 was downregulated compared to NTAT." (PMID 39022679, 2024). "SnoRA12, snoRA47, snoRA80E, and snoRD126 were studied by quantitative real-time PCR (qRT-PCR) in tumor and non-tumor adjacent tissue (NTAT) samples." (PMID 39022679, 2024).
cancer (2 papers, 2021 to 2026). A tumor composed of atypical neoplastic, often pleomorphic cells that invade other tissues. "The combination of miRNA (miR-142-3p), mRNAs (CXCL5, KIF2A, RGS18, APL6IP5, and DAPP1), and snoRNAs (SNORD17, SCARNA12, SNORA6, SNORA12, SCRNA1, SNORD97, SNORD62, and SNORD38A) clearly distinguished the normal samples from the cancer group samples." (PMID 34827689, 2021). "Among the four selected snoRNAs, the combination of SNORD97 with both RGS18 and SNORA12 was the most appropriate for distinguishing between the normal and cancer groups using the MDS plot, heatmap, and ROC curve analyses." (PMID 34827689, 2021).
infection (1 paper, 2014). The state of being infected such as from the introduction of a foreign agent such as serum, vaccine, antigenic substance or organism. "Similar to microarray results, we identified an increase in SNORA12 methylation in response to infection exclusively within the Healthy group." (PMID 24947756, 2014). "Conversely, SNORA12 gene expression was significantly increased during infection within the asthmatics." (PMID 24947756, 2014).
respiratory disease (1 paper, 2014). "Furthermore, because we observed a relationship between SNORA12 gene expression and lung function within our study groups, these findings would suggest that methylation-mediated changes in gene expression caused by underlying respiratory disease may also have functional consequences." (PMID 24947756, 2014).
SNORA12 also shares sentences with these, for which no sentence is quoted: glioma (1 paper); lymphopenia (1); non-alcoholic fatty liver diseases (1).